CD4 (CD4 molecule)
Diseases named in the same sentence as CD4 in open-access papers (continued):
Sharing a sentence is not in itself a finding about the gene and the disease.
allergic asthma (continued). "Although immunopathology of asthma is heterogeneous, one of the first events that defines the initiation and perpetuation of chronic inflammation during allergic asthma is the differentiation of CD4+ T cells toward a type 2 helper cells (Th2) profile." (PMID 28066430, 2016). "CD4+ T cells are thought to play a prominent role in the development of allergic asthma, thus targeting them is considered to be a viable means to combat the disease." (PMID 27255083, 2016). "We observed that the percentage of CD4+ IL-17A+ T cells was higher in allergic asthma patients than in healthy controls (P = .02)." (PMID 23822853, 2013). "PBMCs were isolated from peripheral blood of allergic asthma patients and healthy controls in order to identify IL-17+ CD4+ T cells." (PMID 23822853, 2013). "We proposed to explore the relationship between Fringe and CD4+T cells differentiation regarding the pathogenesis of allergic asthma." (PMID 23071776, 2012). "The onset of allergic asthma is characterized by increased infiltration of naïve CD4+ T lymphocytes into the bronchial mucosa." (PMID 22562770, 2012). "Several studies have shown that CD4+T cells and Th2 cytokines play pivotal roles in the development of allergic asthma." (PMID 23071776, 2012). "Regarding the complex internal environment, the regulation of naïve CD4+T cells differentiation by Notch in vivo, especially in allergic asthma, must be extraordinary profound." (PMID 23071776, 2012). "When naïve CD4+ T cells were co-cultured for 3 days with Der p 1-pulsed MD-DCs from children with allergic asthma, the proliferation of T cells was low compared to unpulsed DCs." (PMID 21612588, 2011). "CD11c+ DCs are critical in activating naïve CD4+ T cells, the products of which are primarily responsible for the symptoms of allergic asthma." (PMID 20659336, 2010). "Additionally, Calca−/−, Ramp1−/−, and CD4+ T cell-specific RAMP1 knockout mice were used from immunological studies in the HDM-induced allergic asthma model." (PMID 41472747, 2025). "As we hypothesized that DMF strengthens the population of Tregs by upregulating Nrf2, which plays a protective role in allergic asthma, we were subjected to exploring the CD4-specific role of Nrf2 in allergic asthma and immune response." (PMID 38711519, 2024). "Interestingly, and consistent with the findings in primary CD4+ T cell in-vitro studies, transcripts encoding STING were induced in ear from the AD model and in whole lung tissue from the allergic asthma model." (PMID 39803487, 2024). "Notably, CD4-specific Nrf2 deletion intensified the allergic asthma symptoms and reduced the in-vitro iTreg differentiation." (PMID 38711519, 2024). "However, our laboratory’s work using the same Foxp3creIL-4Rα−/lox mice in an allergic asthma model revealed that the profiles of CD4 T cells producing IL-17 and IL-10 in both the lymph nodes and lungs were similar." (PMID 39483462, 2024). "CD4+ T helper 2 (Th2) cells and group 2 innate lymphoid cells are considered the main producers of type-2 cytokines that fuel chronic airway inflammation in allergic asthma." (PMID 37612281, 2023). "From these, we believe that while ACC1 is a critical regulator of both conventional CD4+ T cells and iNKT cells in the regulation of allergic asthma, iNKT cells may contribute more to the regulation of allergic asthma compared to CD4+ T cells." (PMID 37917548, 2023). "Moreover, CD4+ Tm is related to the field of allergic asthma, as the proliferation and functional activation of CD4+ Tm influence the release of a series of downstream Th2 cytokines and the cascade of inflammatory reactions." (PMID 37647444, 2023). "Finally, qPCR, flow cytometry, and Westernblotting were used to validate that JGT inhibited Th2 cell differentiationby blocking the JAK1-STAT6 signaling pathway in CD4+ Tcells, ultimately improving allergic asthma." (PMID 38144091, 2023).
allergic asthma (continued). "Therefore, this study examined the role of LCK and its relationship with downstream signaling pathways in CD4+ T cells in a cockroach extract (CE)-induced airway inflammation model of allergic asthma in mice." (PMID 36144198, 2022). "Despite recent work that has explored the participation of tissue-resident memory CD4 T cells in allergic asthma, our knowledge about the contribution of allergen-activated circulatory cells in disease progression and in the maintenance of lung-localized Trm cells is very limited." (PMID 35936001, 2022). "For this reason, we hypothesized that the Imuno TF effect could be restore the balance between Th1/Th2 CD4 T cells response in murine allergic asthma." (PMID 36685604, 2022). "Finally, recent studies provide evidence of a critical function of T follicular helper (Tfh) cells, a subset of CD4+ T cells that help GC B cell responses, in the allergic asthma pathogenesis." (PMID 33643321, 2021). "Moreover, more proportion of dual-positive Th2–Th17 cells can be obtained by conditioned differentiation of mouse CD4+ T cells after classical allergic asthma modeling." (PMID 34394777, 2021). "AT2 MHCII may also play an important role in regulating CD4+ T cell-driven lung diseases in response to respiratory allergens, such as in allergic asthma as well as hypersensitivity pneumonitis." (PMID 34183650, 2021). "The blockade of PD-1/PD-L1 has distinct influences on different CD4+ T cell subsets that could explain some of the variable results observed on allergic asthma by the PD-1 family members." (PMID 34769327, 2021). "Clinical and preclinical studies demonstrate a strong cause and effect relationship between the aberrant expansion of allergen-specific Th2 CD4+ T cells and the development of asthma pathogenesis, thus leading to the idea that Th2 cells play a central role in allergic asthma." (PMID 33643321, 2021). "The activity of CD4+ Th2 lymphocytes dominates the response in typical allergic asthma." (PMID 34595240, 2021). "This novel study was the first to posit the intriguing theory that ORMDL3 overexpression might skew CD4+ T cell differentiation toward a Th2 imbalance, contributing and priming the immune response toward allergic asthma." (PMID 33424845, 2020). "The specific binding of Salp15 to CD4 inhibits the proliferation and differentiation of CD4+ T cells, and can particularly suppress Th2 and inflammatory cytokines, thus playing a predominant role in the development and prevention of allergic asthma." (PMID 31998324, 2019). "Allergic asthma is recognized as a prototypical Th2 disorder, orchestrated by an aberrant adaptive CD4+ T helper (Th2/Th17) cell immune response against airborne allergens, that leads to eosinophilic inflammation, reversible bronchoconstriction, and mucus overproduction." (PMID 30233591, 2018). "Since activated CD4+ T cells are key players in allergic asthma, we determined the specificity of expression of NKp46, NKG2D, ASGM1, and NK1.1 on NK cells, NK1.1+ natural killer T (NKT) cells, and naïve and memory conventional CD4+ T cells in the lungs of naïve and asthmatic mice." (PMID 29444897, 2018). "Furthermore, our results demonstrated that exogenous IL-9 inhibited IFN-γ production by PBMCs or purified CD4+ T cells from children with allergic asthma in a dose-dependent manner." (PMID 28724400, 2017). "The observed effects are consistent with the current understanding of the primary inflammatory lesion in allergic asthma that consists of the accumulation of CD4 T helper type 2 (Th2) lymphocytes and infiltration of mast cells, basophils, monocytes and eosinophils." (PMID 27434719, 2016). "In conclusion, our data supports the view that targeting TRPV1 could be of clinical benefit in patients with allergic asthma, via a possible role in the modulation of CD4+ T cell function." (PMID 27255083, 2016).
allergic asthma (continued). "Increased numbers of CD8-positive T-lymphocytes are found in the airways of COPD patients and the degree of airflow obstruction correlates with their numbers in contrast to allergic asthma, which is characterized by increased numbers of CD4-positive T-lymphocytes." (PMID 24138793, 2013). "Dysregulated type 2 immunity in allergic asthma is characterized by an expansion of CD4+ Th2 cells and cytokines (IL-4, IL-5, IL-13), elevated total and allergen-specific IgE, eosinophilia, and airway inflammation and a counterbalance emergence of B1a cells with regulatory capacity." (PMID 23840604, 2013). "Because endocytic GILT is required for robust CD4+ T cell responses, we reasoned that it might also be important in the generation of allergen-specific CD4+ T cells during allergic asthma responses." (PMID 23326313, 2013). "In this review, we focus on the CD4+ Th2 cells and their products as targets for the development of new drugs to add to the current armamentarium as adjuncts or as potential stand-alone treatments for allergic asthma." (PMID 21867534, 2011). "Allergic asthma is primarily dependent upon the activities of CD4+ T cells." (PMID 20659336, 2010). "On the other hand, CCR4+CD4+ T cells are clearly less frequent in ILD compared to allergic asthma." (PMID 16095529, 2005). "Specifically targeting DCs to modulate CD4+ T cell responses may represent a promising approach to treat allergic asthma where an enhanced Th2 response frequently leads to IgE production (IL-4), eosinophilia (IL-5), mast cell activation (IL-9), and AHR (IL-13)." (PMID 28439267, 2017). "In addition, IL-9-expressing CD4+ T cells did not co-express IL-4, indicating that large percentage of IL-9-expressing CD4+ T cells in children with allergic asthma might be Th9 cells in origin, instead of Th2 cells." (PMID 28724400, 2017). "In addition, we also assessed whether the beneficial effects of EA on allergic asthma could be correlated with CD4+CD25+Foxp3+ regulatory T cells (Treg)." (PMID 22649477, 2012). "Therefore, regulation of CD4+ T cell-mediated immune response itself could be a critical therapeutic target for allergic asthma." (PMID 15921525, 2005). "c-CBL was decreased in blood CD4 + T cells from allergic asthma children and animals, and its overexpression ameliorated OVA-challenged allergic asthma in the neonatal mice." (PMID 39342146, 2024). "To investigate the relationship between CD4+CD44+ memory T cells and allergic asthma, we performed flow cytometry analysis on three different models." (PMID 39632661, 2024). "Recent work shows that both CD4+ and CD8+ cells play a central role in HDM-induced allergic asthma in mice." (PMID 39194564, 2024). "NEt-4IB also reduced the numbers of CD4+ and CD8+ T cells, TNF-α levels, and nuclear factor-κB (NF-κB) expression in lung tissue in a murine model of allergic asthma." (PMID 30606200, 2019). "AOS can be effective in the treatment of allergic asthma in children by increasing the percentage of CD4+CD25+ T cells, CD4+CD25high, CD4+CD25+FoxP3+ Treg cells, and CD4+CD25highCD127low Treg cells." (PMID 30294594, 2018). "The results suggest that AOS consumption increases the percentage of gated CD4+ T cells, CD4+CD25+ T cells, CD4+CD25high, CD4+CD25+FoxP3+ Treg cells, and CD4+CD25highCD127low Treg cells in children with allergic asthma." (PMID 30294594, 2018). "The percentage of CD4+CD25+ T cells and CD4+CD25highCD127low was decreased during acute episode of childhood allergic asthma." (PMID 30294594, 2018). "Meanwhile, DMF failed to exert protective effects on OVA-induced allergic asthma in CD4-specific Nrf2 knock-out mice." (PMID 38711519, 2024). "Although the CD4:CD8 ratio can be increased in human allergic asthma, it is not considered a major disease indicator in human BALC." (PMID 39229267, 2024). "Moreover, CD4+ T cell-specific Cd226-knockout mice were generated and together with littermates were challenged with ovalbumin (OVA) to establish a model of allergic asthma." (PMID 39349422, 2024).
allergic asthma (continued). "Previous reports showed that diesel dust converted allergic asthma from a Th2 to Th17-dominant inflammatory model, and we also found that co-administration of HDM and PM induced the dominant expansion of RORγt+ CD4 T cells." (PMID 33854510, 2021). "Secondly, we determined whether C5aR1+ and C5aR1− cDCs differ in their potential to differentiate CD4+ T cell into Th2 or Th17 effector cells, both of which mediate the maladaptive immune response in HDM-mediated allergic asthma." (PMID 31991941, 2020). "Overall, the results of immune profile analysis showed that PGT treatment reduced the populations of IL-5 and IL-13 producing immune cells, such as CD4+ T cells and ILCs, as well as the total amount of IL-5 and IL-13 producing cells in OVA-induced allergic asthma." (PMID 33374657, 2020). "Both Th1 CD4+T and Tc1 CD8+T cells induced by Ag85A and Mtb32 may downregulate Th2 responses and have benefits for allergic asthma." (PMID 29302700, 2018). "Intracellular staining analysis further showed that HDM induced high percentages of IL-9-expressing CD4+ T cells (0.045 ± 0.008%) in children with allergic asthma, but not in healthy children." (PMID 28724400, 2017). "The characteristic features of allergic asthma, including airway hyperreactivity, histopathology, cytokines (IL-4, IL-5, IL-13, IL-17, and INF-γ), and CD4+CD25+Foxp3+Treg cells in bronchoalveolar lavage fluid (BALF), and downstream proteins of mTORC1/2 signaling were examined." (PMID 29234390, 2017). "In children with allergic asthma an increase in the absolute number of CD8+ T cells expressing CD45RO is associated with a decrease in percentage, but not in the absolute number of CD4+ CD45RO positive cells when compared with healthy controls." (PMID 27799958, 2016). "In contrast, a body of work by Gelfand and colleagues using mainly a systemic sensitisation and topical challenge OVA mouse model of allergic asthma corroborates our results in this HDM model and highlights a role for both CD8+ and CD4+ T cells in AHR and airway inflammation." (PMID 27112462, 2016). "In our allergic asthma cohort CpG -186 emerged as an interesting site based on the significant correlations in methylation between CD4+ lymphocytes and buccal cells at this CpG and not -54." (PMID 24891923, 2014). "Allergic asthma is initiated when allergens such as Der p 1 are inhaled into the airways and internalized by lung-resident APCs, which then process and present these allergens by MHCII to CD4-positive T cells." (PMID 23326313, 2013). "We also found no measurable role for Tim3 in this OVA-induced model of allergic asthma, although unlike Tim1, it was expressed on a population of CD4+CD25+ cells, which would classically be considered to be either T regulatory cells or activated T cells." (PMID 21470319, 2011). "Tg- mice exhibited features of allergic asthma, including elevated cell counts and eosinophils in BAL fluid, increased ova-specific IgE and IgG1 in the serum, and secretion of Th2 and Th17 cytokines upon re-stimulation of CD4+ T cells in vitro." (PMID 20659336, 2010). "The finding that the MAPKs inhibitors very effectively inhibited several cytokines in CD4+ T cells costimulated through CD28 and ICOS, prompted us to investigate whether these selective MAPKs inhibitors may be active in an animal model of allergic asthma." (PMID 15833106, 2005). "In the model of allergic asthma, CD9+ B cells play a role in airway inflammation suppression by inhibiting Th2- and Th17-driven inflammation in an IL-10-dependent manner while MZB cells reduce the CD8 T cell function and IFN-γ+ CD4 T cells during the early stages of Leishmania donovani infection." (PMID 34594327, 2021). "Furthermore, several studies concerning the direct sensitization of HDM have indicated that various factors, such as IL-21 from CD4+ T cells, IL-33 from inflammatory monocytes, TLR4-dependent inflammation, and IRF3 signals, participate in mouse models of allergic asthma." (PMID 31616416, 2019).
allergic asthma (continued). "Previous studies have demonstrated that the development of CD4+Teff cells, such as Th2 and Th17 cells, strongly contribute to airway inflammation, mucus production, AHR, and airway remodeling concomitant with high circulating levels of IgE in patients with allergic asthma." (PMID 30873032, 2019). "Furthermore, IL‐5 and IL‐13 are important CD4 T‐cells and ILC2‐derived cytokines that are involved in eosinophilia, mucus production, and airway hyperreactivity, and they have been suggested as biomarkers and therapeutic targets for type‐2 inflammation‐related disorders such as allergic asthma." (PMID 34873877, 2022). "In the present study, we describe an in vivo mouse model of HDM-induced allergic asthma with a distinct sensitisation and challenge phase characterised by allergen induced airway inflammation and AHR dependent on CD4+ and CD8+ T cells, but not B cells or IgE." (PMID 27112462, 2016). "Interestingly, although the induction of allergic asthma did not result in an accumulation of the IFN-γ-producing Th1 cells in either strain, we found significantly less of those activated CD4 T cells (secreting IFN-γ) in ova-ova March1−/− compared to ova-ova WT." (PMID 29854835, 2018).